CTTNBP2NL (CTTNBP2 N-terminal like)
Description:
Regulates lamellipodial actin dynamics in a CTTN-dependent manner (By similarity). Associates with core striatin-interacting phosphatase and kinase (STRIPAK) complex to form CTTNBP2NL-STRIPAK complexes. STRIPAK complexes have critical roles in protein (de)phosphorylation and are regulators of multiple signaling pathways including Hippo, MAPK, nuclear receptor and cytoskeleton remodeling. Different types of STRIPAK complexes are involved in a variety of biological processes such as cell growth, differentiation, apoptosis, metabolism and immune regulation.
Synonyms: DKFZp547A023
Tractability: PROTAC: ubiquitination databases record sites on it; its protein half-life has been measured.
Gene: Protein-coding gene on chromosome 1 (112,396,202 to 112,463,456, forward strand). Ensembl gene ENSG00000143079.
Subcellular location: Cell projection, lamellipodium; Cytoplasm, cytoskeleton, stress fiber
Subcellular location (Human Protein Atlas): Cytosol; Nucleoli fibrillar center
Gene Ontology:
Molecular function: protein binding; protein phosphatase 2A binding
Biological process: negative regulation of transmembrane transport; negative regulation of transporter activity; protein dephosphorylation; protein localization to actin cytoskeleton
Cellular component: actin cytoskeleton; FAR/SIN/STRIPAK complex; lamellipodium; stress fiber
Genetic constraint (gnomAD): Loss-of-function variants: 12 observed, 19.58 expected, observed/expected ratio (o/e) 0.61, 90% interval 0.39 to 0.99. The upper end of that interval is the gene's LOEUF score, 0.99, which puts it in group 4 of 6, group 1 being the genes least tolerant of losing a copy. Missense variants: 554 observed, 674.57 expected, observed/expected ratio (o/e) 0.82, 90% interval 0.76 to 0.88. Synonymous variants: 264 observed, 265.81 expected, observed/expected ratio (o/e) 0.99, 90% interval 0.9 to 1.1.
Homologues: Orthologues: chimpanzee CTTNBP2NL (99% identical), macaque CTTNBP2NL (99% identical), guinea pig CTTNBP2NL (93% identical), pig CTTNBP2NL (93% identical), dog CTTNBP2NL (91% identical), rabbit CTTNBP2NL (90% identical), mouse Cttnbp2nl (90% identical), rat Cttnbp2nl (89% identical), tropical clawed frog cttnbp2nl (67% identical), zebrafish cttnbp2nlb (44% identical), zebrafish cttnbp2nla (39% identical), Drosophila melanogaster Naus (23% identical). Paralogues in human: FILIP1 (24% identical), FILIP1L (22% identical), LUZP1 (14% identical).
Diseases named in the same sentence as CTTNBP2NL in open-access papers:
CTTNBP2NL is named in the same sentence as 4 diseases in open-access papers, as found by Europe PMC text mining. Sharing a sentence is not in itself a finding about the gene and the disease. The quoted sentences say what the papers report.
periodontitis (1 paper, 2025). An acute or chronic inflammatory process that affects the tissues that surround and support the teeth. "In the Periodontitis group, the most significant genes included CTTNBP2NL, SOS1, RNF213, and IL12RB2." (PMID 40458179, 2025).
cancer (3 papers, 2023 to 2025). A tumor composed of atypical neoplastic, often pleomorphic cells that invade other tissues. "CTTNBP2NL (CTTNBP2 N-terminal-like protein) was also upregulated; this is known to be associated with STRIPAK complexes, which have been broadly linked to metabolism, immune regulation, and cancer tumorigenesis." (PMID 38023136, 2023). "These genes were presumably involved in cancer (SMG6, HCK), cellular growth (CPVL), reproduction (ADGB, CRISP1, CTTNBP2NL, WDR78), and nervous system (AUTS2, CNTNAP2, CPVL, SRGAP2)." (PMID 40149444, 2025).
tumor (1 paper, 2023). "Overexpression of CTTNBP2NL and subsequent STRIPAK complexes could fuel the exhausted CD8+ T cells, thus suppressing immunotherapy effects and promoting tumor progression." (PMID 38023136, 2023).
CTTNBP2NL also shares sentences with these, for which no sentence is quoted: Hypertension (1 paper).